CHD1L (chromodomain helicase DNA binding protein 1 like)
Diseases named in the same sentence as CHD1L in open-access papers (continued):
Sharing a sentence is not in itself a finding about the gene and the disease.
glioma (2 papers, 2020 to 2021). A benign or malignant brain and spinal cord tumor that arises from glial cells (astrocytes, oligodendrocytes, ependymal cells). "CHD1L regulates chromatin relaxation/cell cycle progression and knockdown in glioma cells result in reduced proliferation." (PMID 33055295, 2020). "However, elevated β-catenin expression exhibited in the CHD1L-KD group in glioma." (PMID 33663617, 2021).
metastatic disease (2 papers, 2012 to 2025). "CHD1L is overexpressed in a wide range of malignancies, and this overexpression is strongly associated with tumor progression, metastatic disease, and poor clinical outcomes for breast, ovarian, bladder, lung, colorectal, and many other cancer indications." (PMID 40442742, 2025).
non-small cell lung carcinoma (2 papers, 2019 to 2020). A group of at least three distinct histological types of lung cancer, including non-small cell squamous cell carcinoma, adenocarcinoma, and large cell carcinoma. "Previously, we found an association between CHD1L overexpression and poor patient survival in non-small-cell lung cancer (NSCLC)." (PMID 30718500, 2019).
primary progressive multiple sclerosis (2 papers, 2024 to 2025). A multiple sclerosis that is characterized by steady worsening of neurologic functioning, without any distinct relapses or periods of remission. "The interaction between genetic and epigenetic factors at the 1q21.1 locus affects CHD1L expression and increases susceptibility to primary progressive multiple sclerosis (PPMS)." (PMID 40180689, 2025).
atherosclerosis (1 paper, 2025). A disease characterized by the build-up of fatty material and calcium deposition in the arterial wall resulting in partial or complete occlusion of the arterial lumen. "We next accessed data on monocyte eQTLs from the Multi-Ethnic Study of Atherosclerosis (MESA) cohort and observed a significant correlation between eQTLs increasing CHD1L expression and decreased HIV spVL (p ≤ 0.0022)." (PMID 39825011, 2025).
autism (1 paper, 2023). Persistent deficits in social interaction and communication and interaction as well as a markedly restricted repertoire of activity and interest as well as repetitive patterns of behavior. "In addition, CHD1L is regarded as a candidate gene for autism, ADHD, and congenital anomalies of the kidney and urinary tract." (PMID 37692779, 2023).
breast tumors (1 paper, 2014). "IHC staining was used to detect the expression of CHD1L protein in 179 human breast tumors and 65 matched normal breast tissue specimens." (PMID 25153161, 2014).
CHARGE syndrome (1 paper, 2024). CHARGE syndrome is a multiple congenital anomaly syndrome characterized by the variable combination of multiple anomalies, mainly Coloboma; Choanal atresia/stenosis; Cranial nerve dysfunction; Characteristic ear anomalies (known as the major 4 C's). "Aberrations in CHD7, an ATP-dependent eukaryotic enzyme attributed to the CHD family whose structure is homologous to that of CHD1L, have been confirmed to cause CHARGE syndrome, where “G” represents genital and urinary abnormalities." (PMID 39342328, 2024).
colon cancer (1 paper, 2022).
cystadenoma (1 paper, 2020). A benign or borderline cystic epithelial neoplasm arising from the glandular epithelium. "Using a large cohort of clinical EOC tissue, borderline tumors, cystadenomas tissue, and normal ovarian tissue for control, the expression dynamics of CHD1L were evaluated using immunohistochemistry (IHC)." (PMID 32922205, 2020).
Epileptic encephalopathy (1 paper, 2014). A condition in which epileptiform abnormalities are believed to contribute to the progressive disturbance in cerebral function. "However, it was noted that CHD2, a protein that belongs to the same family as CHD1L, has been strongly implicated in epileptic encephalopathy in several recent studies." (PMID 24885232, 2014).
esophageal squamous cell carcinoma (1 paper, 2021). Esophageal squamous cell carcinoma (ESCC) is a type of esophageal carcinoma (EC) that can affect any part of the esophagus, but is usually located in the upper or middle third. "However, the downregulation of CHD1L enhanced cisplatin cytotoxicity of esophageal squamous cell carcinoma cells by inhibiting the glycolysis of PI3K/AKT pathway." (PMID 33663617, 2021).
gall bladder adenocarcinoma (1 paper, 2009). "Several different types of tumors were found in CHD1L-transgenic mice including HCC, salivary, colon, uterine, and gall bladder adenocarcinoma, and rhabdomyosarcoma." (PMID 19701453, 2009).
HIV-1 infection (1 paper, 2023). The type species of lentivirus and the etiologic agent of acquired immunodeficiency syndrome (AIDS). "Given its proximity to the association peak and plausible functional connection to viral replication, we sought to assess the biological relevance of CHD1L in HIV-1 infection." (PMID 37532928, 2023). "We observed a stepped decrease in HIV-1-encoded GFP after increasing exogenous expression of CHD1L, supporting CHD1L as an inhibitor of HIV-1 infection." (PMID 37532928, 2023). "KO of CHD1L expression in in vitro HIV-1 infection models enhanced viral replication, and rescue experiments showed a decrease in viral infection with exogenous CHD1L expression." (PMID 37532928, 2023).
invasive breast carcinoma (1 paper, 2014). A carcinoma that infiltrates the breast parenchyma. "In this study, immunohistochemical staining for CHD1L expression was performed on tissue microarrays containing 179 primary invasive breast cancers and 65 matched normal breast tissue specimens." (PMID 25153161, 2014).
invasive ductal carcinoma (1 paper, 2015). "Association between CHD1L expression and clinical features of invasive ductal carcinoma patients." (PMID 26599012, 2015). "The correlations between the expression of CHD1L and the clinicopathological parameters of invasive ductal carcinoma were analyzed." (PMID 26599012, 2015). "CHD1L was expressed in 112 of 268 invasive ductal carcinoma tissues (41.8%) and 32 of 150 normal mammary glands (21.3%)." (PMID 26599012, 2015). "Immunohistochemistry was performed to detect the expression of CHD1L in patients with invasive ductal carcinoma and normal mammary glands." (PMID 26599012, 2015). "The CHD1L expression in normal mammary glands was significantly lower than that in invasive ductal carcinoma (P < 0.001)." (PMID 26599012, 2015).
multiple myeloma (1 paper, 2021). "CHD1L as a potent anti-apoptotic and pro-proliferative factor, CHD1L overexpression is correlated with the increase of chemotherapy resistance in myeloma, NSCLC and ESCC." (PMID 33663617, 2021). "Bortezomib decreased the protein levels of CHD1L, but cell adhesion increased the expression levels of CHD1L, overexpression of CHD1L contributes to cell adhesion-mediated drug resistance (CAM-DR) in multiple myeloma cells." (PMID 33663617, 2021).
neuroblastoma (1 paper, 2024). Neuroblastoma (NB) is the most common solid, extracranial childhood tumor. "Interestingly, a previous study found CHD1L germline alterations among three pediatric patients diagnosed with neuroblastoma, retinoblast-oma, and a Wilms tumor, respectively." (PMID 39037077, 2024).
ovarian cystadenoma (1 paper, 2020). A benign ovarian surface epithelial-stromal tumor characterized by the presence of cystic structures lined by serous epithelial cells, mucinous columnar epithelial cells, or endometrial-type well-differentiated cells. "In the present study, we increased our sample size and further confirmed that the degree of CHD1L overexpression increased sequentially from the normal ovarian tissues, to ovarian cystadenoma, to borderline tumors, and finally to EOC tissues." (PMID 32922205, 2020).
ovarian serous cancer (1 paper, 2021). "Using the bioinformatics analyses, we found that the expression of CHD1L mRNA and protein in ovarian serous cancer was significantly higher than that in normal ovarian tissues, which was similar to our previous study based on tissue microarrays." (PMID 34034740, 2021).
ovarian serous cystadenocarcinoma (1 paper, 2021). A malignant serous cystic epithelial neoplasm arising from the ovary. "After stratification by tumor grade, CHD1L mRNA expression in grade II and grade III ovarian serous cystadenocarcinoma were significantly higher than normal ovarian tissue or grade I ovarian serous cystadenocarcinoma." (PMID 34034740, 2021).
pulmonary stenosis (1 paper, 2023). "Overexpression of CHD1L was discovered in the tetralogy of Fallot (TOF), double-outlet right ventricle, and infundibular pulmonary stenosis." (PMID 37692779, 2023).
renal dysplasia (1 paper, 2022). Renal dysplasia is a form of renal malformation in which the kidney(s) are present but their development is abnormal and incomplete. "The phenotypes of individuals carrying the CHD1L gene variant is very heterogenous: bilateral kidney malrotation, right renal dysplasia, horseshoe kidneys, right duplex collecting system, right MCDK, left UVJO and PUV." (PMID 34979951, 2022).
serous ovarian carcinoma (1 paper, 2012). "The positive expression of CHD1L protein expression increasingly presented from mucinous/serous ovarian carcinoma to others types of tumor, including undifferentiated ovarian carcinoma." (PMID 23020525, 2012).
skin cancer (1 paper, 2023). "The generated data revealed that, in colon, liver, lung, and skin cancers, CHD1L showed a significantly upregulated expression when we set a comparison between normal and tumor tissues and kept this trend in the metastatic versus the tumor tissues." (PMID 37033447, 2023). "Not only tumor stage but also tumor metastasis showed a positive correlation with CHD1L expression in colon, liver, lung, and skin cancers." (PMID 37033447, 2023).
squamous cell carcinoma (1 paper, 2015). A carcinoma arising from squamous epithelial cells. "Using this criteria, CHD1L overexpression was observed in 98/233 (42.1%) of the NSCLCs, 58/109 (53.2%) of the adenocarcinomas (ADCs) and 25/89 (28.1%) of the squamous cell carcinomas (SCCs), respectively." (PMID 26360781, 2015). "The frequency of CHD1L overexpression (53.2% vs. 28.1%, P = 0.002) and amplification (25.2% vs. 8.2%, P = 0.020) in adenocarcinoma (ADC), was much higher than that in squamous cell carcinoma (SCC)." (PMID 26360781, 2015).
cancer (39 papers, 2009 to 2025). A tumor composed of atypical neoplastic, often pleomorphic cells that invade other tissues. "The multifaceted survival advantages conferred by CHD1L likely contribute to the aggressive behavior and treatment resistance observed in many cancers where CHD1L is implicated." (PMID 40442742, 2025). "Clinical studies show that CHD1L is associated with more aggressive cancers and poor prognosis across multiple cancer types." (PMID 40442742, 2025). "Several studies have shown that loss or reduction of CHD1L sensitizes cells to PARPi in homologous recombination (HR)-deficient cancer cells while overexpression confers resistance." (PMID 39201277, 2024). "Elevated CHD1L expression in patients is linked to poor prognosis, accelerated disease progression, metastasis, and decreased survival rates across multiple cancers, including CRC." (PMID 39684869, 2024). "CHD1L is a newly discovered oncogene that has been linked to cancer via apoptosis inhibition, G1/S transition, and uncontrolled cell proliferation." (PMID 37923899, 2023). "We will provide an overview of current understanding about CHD1L on structure, characteristics, function and the molecular mechanisms underlying CHD1L in cancer development in this review." (PMID 33663617, 2021). "It should also be noted, however, that other macrodomain-containing proteins such as PARG and CHD1L (ALC1) have been previously linked closely to cancer." (PMID 32151005, 2020). "Notably, a CHD1L knockout mouse model for investigating homologous recombination deficiency cancers has been generated." (PMID 39342328, 2024). "Although CHD1L expression has been extensively characterized in human cancers, the molecular mechanisms underlying aberrant CHD1L expression induced in human malignancies remain unknown." (PMID 32922205, 2020). "Regarding CHD1L, this gene encodes a DNA helicase protein involved in the relaxation following DNA damage and ultimately, in DNA repair, and its overexpression has been linked to several types of cancers." (PMID 29922639, 2018). "How these mutations change CHD1L biological functions in cancer cells remains to be explored." (PMID 24359616, 2013). "Clinical studies and analyses of patient samples show that elevated CHD1L expression is correlated with poor prognosis and increased metastatic potential across many cancer types." (PMID 40072047, 2025). "Nonetheless, if RNAi gene silencing becomes a clinically valid therapeutic strategy in human disease, CHD1L will be a strong target candidate for cancer treatment." (PMID 40442742, 2025). "In the context of disease, aberrant CHD1L promotes adaptability, survival, and immune evasion under stress and therapeutic pressure, particularly in cancer." (PMID 40442742, 2025). "These developmental functions rely on CHD1L’s chromatin remodeling, a mechanism later exploited in cancer to drive transcriptional reprogramming and tumor progression." (PMID 40442742, 2025). "One proposed strategy to fight the malignant activity conferred by CHD1L in cancer is to prevent its expression using gene therapy." (PMID 40442742, 2025). "Conversely, CHD1L knockdown upregulates E-cadherin and suppresses vimentin and N-cadherin, indicating EMT reversal and loss of cancer stem cell traits." (PMID 40442742, 2025). "Among all biological contexts in which CHD1L has been studied, its role in cancer is by far the most extensively characterized." (PMID 40442742, 2025). "CHD1L has a variety of oncogenic functions that promote tumor progression, metastatic potential, cancer cell survival, and resistance to treatment." (PMID 40442742, 2025). "The versatile function of CHD1L in cancer cell survival distinguishes this chromatin remodeler as both a prognostic biomarker and a prime molecular target for anticancer therapy." (PMID 40442742, 2025). "Upregulation of CHD1L in cancer cells correlates with increased vimentin and slug expression, along with decreased E-cadherin, suggesting a shift toward EMT." (PMID 40442742, 2025).
cancer (continued). "As such, CHD1L has emerged as a master regulator of PARthanatos and a gatekeeper of cancer cell viability under stress." (PMID 40442742, 2025). "The knockdown of CHD1L using shRNA suppressed proliferation, motility, invasion, and survival in several different cancer lines." (PMID 40442742, 2025). "An alternative to gene therapy for targeting CHD1L in cancer is the use of small molecule inhibitors." (PMID 40442742, 2025). "Diseased cells, such as in cancer, co-opt this pathway via CHD1L-driven TCF/LEF transcription to promote survival under therapeutic stress." (PMID 40442742, 2025). "CHD1L contributes to many hallmarks of cancer, including enhanced survival, evasion of programmed cell death, metastatic potential, evasion of the immune response, and MDR." (PMID 40442742, 2025). "Experimental studies have shown that knockdown of CHD1L in cancer cell lines reduces tumor growth and increases sensitivity to both chemotherapy and targeted therapy." (PMID 40442742, 2025). "This comprehensive body of evidence has sparked increasing interest in the development of therapeutic strategies to target CHD1L in cancer." (PMID 40442742, 2025). "Although both RNAi strategies have been utilized to study the cellular function of CHD1L in vitro, it has yet to be effectively validated as a form of cancer treatment in humans." (PMID 40442742, 2025). "A growing body of evidence links CHD1L as an oncogenic protein and therapeutic target in a multitude of cancers." (PMID 40072047, 2025). "Studies of patient tumor samples report CHD1L overexpression in breast, pancreatic, non-small cell lung, and many other cancer indications." (PMID 40442742, 2025). "By trapping CHD1L and disrupting chromatin remodeling, CHD1Li blocks the repair mechanisms that cancer cells rely on to survive chemotherapy-induced damage." (PMID 39684869, 2024). "The combination of standard of care chemotherapy drugs with CHD1Li represents a promising advancement in future therapeutic strategies for CRC and other cancers driven by CHD1L." (PMID 39684869, 2024). "The results from both databases indicate that an overall poor clinical outcome is expected with CHD1L expression in cancer patients." (PMID 37033447, 2023). "Result and discussion: The results demonstrated that CHD1L is a highly expressed gene across several types of tumors and that was correlated with a poor prognosis for most cancer patients." (PMID 37033447, 2023). "After analyzing the differential expression of CHD1L in normal and cancerous tissue, we aimed to explore the relationship between CHD1L expression and the cancer stage." (PMID 37033447, 2023). "For instance, higher levels of CHD1L, HDAC1, MUTYH, NEIL3, POLR2L, RUVBL1, and SPP1 expression in cancer cells have been linked to higher levels of drug resistance to nelarabine, acridine, chlorambucil, dexrazoxane, cladribine, and other drugs." (PMID 37923899, 2023). "This comprehensive study demonstrates the predicted molecular roles of CHD1L in several cancer types in addition to its influence on clinical prognosis." (PMID 37033447, 2023). "CHD1L also contributes to stemness in pluripotent cells, it regulates pluripotency, differentiation and invasiveness of cancer cells; furthermore, inhibition of CHD1L was reported to down-regulate SNAI2 expression." (PMID 35864202, 2022). "The role of CHD1L has been thoroughly described in cancer literature to drive tumour proliferation lead to poor cancer prognosis possibly by regulating immune factors in regulating apoptosis such as CD8+ T-cell populations and IL-6 levels." (PMID 35354798, 2022).